FCRL5 (Fc receptor like 5)
Description:
Plays an important role in B-cell response to antigen that acts both as a negative or positive coreceptor. Inhibits B-cell receptor (BCR) signaling in the absence of CR2 stimulation but engagement with CR2 and the BCR lead to a superior calcium response compared to CR2 and BCR costimulation. May be involved in B-cell development and differentiation in peripheral lymphoid organs and may be useful markers of B-cell stages. May have an immunoregulatory role in marginal zone B-cells. May play a role in fertilization (By similarity).
Synonyms: FcRH5; CD307e; IRTA2; BXMAS1; CD307; PRO820
Tractability: Antibody: UniProt places it where antibodies can reach, with high confidence; its Gene Ontology location is reachable by antibodies, with high confidence; UniProt predicts a signal peptide or a membrane-spanning region.
Gene: Protein-coding gene on chromosome 1 (157,513,377 to 157,552,515, reverse strand). Ensembl gene ENSG00000143297.
Subcellular location: Cell membrane
Gene Ontology:
Molecular function: coreceptor activity; protein binding; transmembrane signaling receptor activity
Biological process: B cell activation; cell surface receptor signaling pathway; immune response
Cellular component: cell surface; plasma membrane; receptor complex; external side of plasma membrane
Genetic constraint (gnomAD): Loss-of-function variants: 77 observed, 92.28 expected, observed/expected ratio (o/e) 0.83, 90% interval 0.69 to 1.01. The upper end of that interval is the gene's LOEUF score, 1.01, which puts it in group 4 of 6, group 1 being the genes least tolerant of losing a copy. Missense variants: 1,152 observed, 1,216.9 expected, observed/expected ratio (o/e) 0.95, 90% interval 0.9 to 0.99. Synonymous variants: 464 observed, 483.57 expected, observed/expected ratio (o/e) 0.96, 90% interval 0.89 to 1.04.
Homologues: Orthologues: chimpanzee FCRL5 (95% identical), macaque FCRL5 (87% identical), rabbit FCRL5 (56% identical), dog FCRL5 (37% identical). Paralogues in human: FCRL3 (36% identical), FCRL2 (25% identical), FCRL4 (23% identical), FCRL1 (21% identical), FCRL6 (15% identical), PECAM1 (13% identical), FCGR1A (12% identical), FCRLB (11% identical), FCRLA (10% identical), FCGR2B (9% identical), FCGR2C (8% identical), FCGR2A (8% identical), and 5 more.
Diseases named in the same sentence as FCRL5 in open-access papers:
FCRL5 is named in the same sentence as 60 diseases in open-access papers, as found by Europe PMC text mining. Sharing a sentence is not in itself a finding about the gene and the disease. The quoted sentences say what the papers report.
myeloma (35 papers, 2017 to 2025). "Interestingly, the corresponding gene FCRL5 is located on chromosome 1q, thus FcRH5 is highly expressed in patients with amplification of 1q21, a poor-risk marker in myeloma." (PMID 38800372, 2024). "FcRH5, also referred to as FcRL5, CD307, or IRTA2 (Immunoglobulin Superfamily Receptor Translocation Associated 2), is a membrane protein of an unknown function, which is exclusively expressed in B-cell lineage, including myeloma cells." (PMID 32659909, 2020). "FCRL5, also known as CD307, is encoded by the immunoglobulin superfamily receptor translocation-associated 2 (IRTA2) gene and was originally cloned from myeloma cell lines." (PMID 32841219, 2020). "Analysis of blood and tissue samples by the Pastan laboratory identified elevated levels of soluble and surface bound FCRL5 in multiple myeloma, CLL, and mantle cell lymphoma patient samples." (PMID 33162991, 2020). "This is despite the fact that they represent a potential biomarker of clinical response for rituximab in rheumatoid arthritis and the observation that FCRL5 gene expression is strongly upregulated on the bone marrow plasma cells of multiple myeloma and Burkitt Lymphoma." (PMID 33889124, 2021). "However, preclinical studies with a bispecific FCRL5/CD3 mAb has shown encouraging activity against patient myeloma cells, can deplete B cells and bone marrow plasma cells in cynomolgus monkeys, and exhibits enhanced activity when combined with PD-L1 blockade." (PMID 33162991, 2020). "Studies targeting FCRL5 in myeloma have been conducted by investigators at Genentech." (PMID 33162991, 2020). "Bispecific antibodies developed for multiple myeloma currently target B-cell maturation antigen (BCMA), G protein–coupled receptor, class C, group 5, member D (GPRC5D), Fc receptor-like 5 (FcRL5), or CD-38." (PMID 39754658, 2025). "Fc receptor-like 5 (FCRL5), a surface marker found specifically on plasma cells in myeloma, has attracted attention as a possible therapeutic approach." (PMID 38212320, 2024). "Anti-FcRL5/CD3 TDB (BFCR4350A) induced mild/moderate cytokine release immediately after administration in primates, effectively killing myeloma cells and marrow plasma cells, but the effect in mouse models was significantly limited." (PMID 38280847, 2024). "These early studies also demonstrated dysregulated FCRL5/IRTA2 transcript expression in follicular lymphoma and myeloma cell lines with 1q21 abnormalities." (PMID 33162991, 2020). "For other neoplasms as multiple myeloma (MM), some possible targets for immunotherapy include B-cell maturation antigen (BCMA), G protein-coupled resector 5D (GPR5D), CD38, and Fc receptor-like 5 (FCRL5)." (PMID 35745815, 2022). "While FCRL5 and GPRC5D TCRTs have exhibited impressive anti-myeloma responses, especially in patients with prior BCMA therapy exposure, GPRC5Dlow/neg progressive disease has already been documented, and there is the potential for antigen escape through FCRL5 cleavage." (PMID 39095991, 2024). "A Phase 1 study of this anti-FCRL5-MMAE drug compound (DFRF4539A) in relapsed and refractory multiple myeloma patients (n = 39) showed tolerability as a single agent, but demonstrated limited activity and may not be a successful strategy for myeloma." (PMID 33162991, 2020).
malaria (11 papers, 2015 to 2023). Malaria is a serious and sometimes fatal disease caused by a parasite that commonly infects a certain type of mosquito which feeds on humans. "Curiously, the FCRL5 marker that was previously associated with impaired B cell responses in malaria, was highly expressed in a naïve B cell and atypical MBC cluster, and in a higher frequency in mock individuals compared to PfRAS vaccinated groups." (PMID 37195999, 2023). "In malaria-exposed children we found that T-bethi B cells express markers that are known to be associated with atypical MBCs (FCRL5, FCGR2B, CD11c, CXCR3 and CD95)." (PMID 28953967, 2017). "Additionally, FCRL5+ atypical MBCs with reduced function have been associated with increased exposure to malaria." (PMID 37195999, 2023). "In this study, we focused on P. falciparum patients to test whether malaria-associated anemia correlates with the autoimmune anti-PS response and with FcRL5+T-bet+ B-cells, which would be consistent with a causal relationship." (PMID 31713516, 2019). "However, some of the IgG+ MBC subsets also showed an increase in FcRL5 expression during the malaria-free period, and it can therefore not be concluded that the increase in FcRL5 expression in these B cell subsets was caused by the malaria episode." (PMID 34758841, 2021). "Moreover, in an independent experiment (n = 10 Malian children) T-bethi B cells of malaria-exposed children expressed markers that are known to be associated with atypical MBCs, with higher surface expression of FCRL5, CD11c, CXCR3 and CD95, and decreased expression of CD35, CD40, CXCR5 and CCR7." (PMID 28953967, 2017). "We have performed a detailed molecular characterization of malaria-associated atMBCs, beginning with an unbiased transcriptome-wide comparison with classical MBCs and leading to functional characterization of atMBC subsets defined by differential expression of FCRL5." (PMID 25993340, 2015). "The mechanisms through which PS antibodies are produced during malaria are not completely understood, but atypical FcRL5+T-bet+ B cells have been shown to be their source in malaria-naïve individuals." (PMID 37091678, 2023). "A higher frequency of FCRL5+ AM B cells was also observed in chronic infections such as malaria and hepatitis C in addition to common variable immunodeficiency and autoimmune conditions, including rheumatoid arthritis and SLE." (PMID 35899045, 2022). "In both children, FcRL5− IgG+ classical MBCs showed the largest changes over time, both in contraction during the malaria-free period (− 8%) and in expansion after a malaria episode (+ 6%) as compared to FcRL5+ IgG+ classical MBCs and IgG+ atypical MBCs." (PMID 34758841, 2021). "Here, the impact of a malaria episode on the expression of FcRL5 on the cell surface of naïve B cells (CD21+CD27−), classical MBCs (CD21+CD27+), activated MBCs (CD21−CD27+), and atypical MBCs (CD21−CD27−) was evaluated by flow cytometry." (PMID 34758841, 2021). "The observation that FcRL5 expression increased in all IgM+ MBC subsets after malaria raises the question of what the function of this marker is." (PMID 34758841, 2021). "For IgG+ atypical MBCs, the strongest connection was observed with pre-malaria FcRL5+ IgG+ classical MBCs." (PMID 34758841, 2021). "IgG+ atypical MBCs present after a malaria episode mainly originated from FcRL5+ IgG+ classical MBCs." (PMID 34758841, 2021). "Previously, it was reported that classical and atypical MBC populations in malaria-experienced individuals were heterogeneous in FcRL5 expression and showed related functional differences." (PMID 34758841, 2021). "The percentage of FcRL5+ cells also increased after malaria among IgG+ B cells (median, 11%; range, 5–24%)." (PMID 34758841, 2021). "For IgM+ atypical MBCs, clonal connections were observed with naïve B cells, but also with FcRL5− IgM+ classical MBCs present before the malaria episode." (PMID 34758841, 2021).
malaria (continued). "During the malaria-free period (0 months to 3 months), the percentage of IgM+ FcRL5+ cells decreased or remained stable, both when calculated relative to all IgM+ B cells or MBC subsets and in each MBC subset separately (median, − 3.3%; range, − 26–5%)." (PMID 34758841, 2021). "Following malaria, FcRL5 expression increased in all IgM+ MBC subsets analysed here: classical, activated, and atypical MBCs, while results for IgG+ MBC subsets were inconclusive." (PMID 34758841, 2021). "In this study, IgG+ atypical MBCs present after malaria seem to be predominantly derived from FcRL5+ IgG+ classical MBCs." (PMID 34758841, 2021). "In summary, our results provide the first mechanistic evidence of autoimmune-mediated malaria anemia in patients, and suggest that atypical T-bet+FcRL5+ B-cells are major promoters of this pathology in P.-falciparum-infections." (PMID 31713516, 2019). "Earlier work also showed that in addition to FcRL5 (a potential inhibitory receptor) the expression of two inhibitory receptors, CD85j and CD22, were upregulated in malaria-associated atypical MBCs as compared to classical MBCs." (PMID 31068937, 2019). "By delineating the transcriptional landscape of atMBCs and identifying expression of FCRL5 as a key marker of dysfunction, we provide a foundation for improving our understanding of the role of these cells in immunity to malaria." (PMID 25993340, 2015). "In contrast, the widely used anti-FCRL4 antibody clone 2A6, which was employed in previous malaria-associated atMBCs studies, bound strongly to both FCRL4- and FCRL5-expressing cell lines." (PMID 25993340, 2015). "Therefore, the effect of a malaria episode on FcRL5 expression in various B cell subsets was determined first." (PMID 34758841, 2021). "In contrast, IgM+ FcRL5+ cells increased in frequency after the malaria episode (median, 17%; range, 11–23%), suggesting that malaria may drive FcRL5 expression in all IgM+ MBCs." (PMID 34758841, 2021). "Here, a longitudinal analysis of FcRL5 expression in various B cell subsets was performed in two children from a high transmission region in Uganda over a 6-month period in which both children experienced a malaria episode." (PMID 34758841, 2021). "Interestingly, FcRL5 expression consistently increased on all IgM+ memory B cells subsets after malaria, while results for IgG+ memory B cell subsets were less uniform." (PMID 34758841, 2021). "Malaria appeared to induce the expression of FcRL5 on all IgM+ MBC subsets analysed here." (PMID 34758841, 2021). "Interestingly, some evidence suggests that FCRL5 is a receptor for IgG, which circulates at high levels during malaria." (PMID 25993340, 2015). "Hence studying these FcRL5+T-bet+ B-cells during acute stage malaria in a population from a non-endemic area, such as European travelers, represents a unique opportunity to study the antibody specificity that results from recent primary activation." (PMID 31713516, 2019). "However, emerging data suggests that the array of inhibitory receptors expressed by atypical MBCs varies by disease; for example, malaria-associated atypical MBCs upregulate the expression of FCRL3 and FCRL5 rather than FCRL4." (PMID 28953967, 2017).
autoimmune disease (8 papers, 2012 to 2025). A disorder resulting from loss of function or tissue destruction of an organ or multiple organs, arising from humoral or cellular immune responses of the individual to their own tissue constituents. "Among the ABC upregulated genes, we focused on Fcrl5, an ortholog of hFcrl3 whose upregulated expression is closely associated with autoimmune disease development." (PMID 37841260, 2023). "Fcrl5—a gene whose homologs are associated with human autoimmune diseases—is highly expressed in age/autoimmunity-associated B cells (ABCs), an autoreactive B cell subset." (PMID 37841260, 2023). "While FCRL5 has mostly been characterized in B cells and B cell lymphomas, polymorphisms have also been reported to be associated with autoimmune diseases such as ankylosing spondylitis, suggesting an immunoregulatory role." (PMID 22829946, 2012). "Additionally, overexpressed genes such as IKAROS family zinc finger 3 (IKZF3), MER proto-oncogene, tyrosine kinase (MERTK), and Fc receptor-like 5 (FCRL5) all have risk alleles associated with MS or other autoimmune diseases." (PMID 39596026, 2024). "Upregulation of the gene FCRL5 has been associated with autoimmune disease, which may be an important factor in pregnancy in the context of anti-fetal rejection, and the question remains of whether increasing vitamin D status could mitigate the upregulation of this gene." (PMID 40429621, 2025). "Our findings that Fcrl5 is more highly expressed in ABCs of aged mice and that B cell-specific Fcrl5 Tg mice show an autoimmune phenotype highlight the importance of the pathogenesis of autoimmune diseases." (PMID 37841260, 2023). "Given that TLR7/9 activation has been implicated in the development and regulation of autoimmune diseases via anergy disruption and that hFcrl signaling increases TLR-mediated B cell activation, we investigated the effect of Fcrl5 on TLR7/9 signaling." (PMID 37841260, 2023). "Our study provides important insights into the role of Fcrl5 in breaking B cell anergy and its effect on the pathogenesis of autoimmune diseases." (PMID 37841260, 2023). "Here, we demonstrated that Fc receptor-like 5 (Fcrl5) upregulation contributes to autoimmune disease pathogenesis by disrupting B cell anergy." (PMID 37841260, 2023). "This study provides important insights into the role of Fcrl5 in breaking B cell anergy and its effect on the pathogenesis of autoimmune diseases." (PMID 37841260, 2023). "Here, we demonstrated that Fcrl5 overexpression in B cells contributed to autoimmune disease development." (PMID 37841260, 2023). "Studies have suggested that FCRL5 may be involved in autoimmune diseases, allergic reactions, and other immune-related disorders." (PMID 40760602, 2025). "To investigate whether upregulated Fcrl5 expression affects autoimmune disease progression, we used the TLR7 agonist imiquimod-induced SLE-like model." (PMID 37841260, 2023). "Thus, ABCs, potential drivers of autoimmune diseases, show high Fcrl5 expression." (PMID 37841260, 2023). "However, the role of Fcrl5 expression in B cells in the pathogenesis of autoimmune disease remains unknown." (PMID 37841260, 2023). "Given our finding that Fcrl5 overexpression disrupts immune tolerance, it is conceivable that Fcrl5 in anergic B cells, which are inherently restrained from autoreactive responses, may facilitate BCR signaling and precipitate autoimmune diseases." (PMID 37841260, 2023).
Autoimmunity (5 papers, 2021 to 2024). The occurrence of an immune reaction against the organism's own cells or tissues. "By generating B cell-specific Fcrl5 transgenic mice, we demonstrated that Fcrl5 overexpression in B cells caused systemic autoimmunity with age." (PMID 37841260, 2023). "Our results support the role of the FCRL5 locus in MS predisposition and extend the evidence of its influence on autoimmunity." (PMID 33889124, 2021). "Given that ICI-ILD is considered a type of irAE, it is reasonable to hypothesize that FCRL5+ B cells may be one of the immune cells associated with autoimmunity." (PMID 38607373, 2024). "This evidence indicates the pathogenic role of FCRL5 on autoimmunity." (PMID 36949950, 2023). "Nevertheless, our results suggest that polymorphisms in the FCRL5 gene may be a risk factor for autoimmunity, and that FCRL5-dependent mechanisms may be involved in MS development." (PMID 33889124, 2021). "Previous research has suggested that FCRL5+ B cells contribute to the pathogenesis of autoimmune disorders." (PMID 38607373, 2024). "Recent evidence indicated that CD11c+ DN B cells and FCRL5+ B cells are involved in the development of autoimmune conditions." (PMID 36949950, 2023). "Thus, Fcrl5 is a potential regulator of B cell-mediated autoimmunity by regulating B cell anergy." (PMID 37841260, 2023). "Therefore, Fcrl5 upregulation in B cells reversed the anergic state of autoreactive B cells in the MD4/ML5/Fcrl5 Tg mice, allowing them to produce autoantibodies and potentially present self-antigens that may be involved in autoimmunity." (PMID 37841260, 2023). "The observations that TLR7-driven autoimmunity was accelerated by B cell-specific Fcrl5 overexpression in mice and that TLR7/9-mediated B cell activation was facilitated by Fcrl5 cross-linking are consistent with many previous findings." (PMID 37841260, 2023). "Mechanistically, Fcrl5 overexpression disrupted B cell anergy and facilitated TLR signaling, possibly contributing to autoimmunity." (PMID 37841260, 2023). "Hence, Fcrl5 promotes B cell activation in response to TLR signaling, suggesting that Fcrl5 upregulation may contribute to TLR-mediated B cell activation and autoimmunity." (PMID 37841260, 2023).
rheumatoid arthritis (5 papers, 2020 to 2024). A chronic, systemic autoimmune disorder characterized by inflammation in the synovial membranes and articular surfaces. "In both rheumatoid arthritis and granulomatosis with polyangiitis and microscopic polyangiitis, increased expression of FCRL5 was indicative of a positive response to rituximab." (PMID 38607373, 2024). "Higher FCRL5 expression predicted response to rituximab in rheumatoid arthritis and granulomatosis with polyangiitis and microscopic polyangiitis." (PMID 36949950, 2023). "Baseline expression of FCRL5, a marker of naive and memory B cells, was shown to predict response to rituximab (RTX) in rheumatoid arthritis." (PMID 32841219, 2020).